SPATA31D3 (SPATA31 subfamily D member 3)
Description:
May play a role in spermatogenesis.
Synonyms: FAM75D3; FLJ44082
Tractability: Antibody: UniProt predicts a signal peptide or a membrane-spanning region.
Gene: Protein-coding gene on chromosome 9 (81,943,500 to 81,950,093, forward strand). Ensembl gene ENSG00000186788.
Subcellular location: Membrane
Gene Ontology:
Cellular component: membrane
Genetic constraint (gnomAD): Loss-of-function variants: 0 observed, 0.29 expected, observed/expected ratio (o/e) 0, 90% interval 0 to 1.87. That is too few expected variants to judge how well the gene tolerates losing a copy. Missense variants: 84 observed, 142.79 expected, observed/expected ratio (o/e) 0.59, 90% interval 0.49 to 0.7. Synonymous variants: 23 observed, 54.44 expected, observed/expected ratio (o/e) 0.42, 90% interval 0.3 to 0.6.
Homologues: Orthologues: mouse Spata31f3 (5% identical). Paralogues in human: SPATA31D4 (99% identical), SPATA31D1 (91% identical), SPATA31A6 (26% identical), SPATA31A1 (26% identical), SPATA31A3 (26% identical), SPATA31A5 (26% identical), SPATA31A7 (26% identical), SPATA31E1 (22% identical), SPATA31C1 (21% identical), SPATA31C2 (21% identical), SPATA31F1 (17% identical), SPATA31F3 (3% identical).